IL6 (interleukin 6)
Diseases named in the same sentence as IL6 in open-access papers (continued):
Sharing a sentence is not in itself a finding about the gene and the disease.
rheumatoid arthritis (continued). "Treatment with an approved TNFα blocking antibody showed marked reduction in the levels of IL-6, IL-1β, and IL-17 and the expression level of STAT3 phosphorylation in relation to Th17 cell differentiation in patients with rheumatoid arthritis." (PMID 25436214, 2014). "Patients with rheumatoid arthritis (RA) report daily variations in their symptoms, experiencing greater joint pain, stiffness, and functional disability in the mornings, which is accompanied by fluctuations in circulating IL6 concentration." (PMID 25401152, 2014). "In the setting of rheumatoid arthritis, pro-inflammatory cytokine levels are elevated, which includes IFN-γ, TNF-α, IL-6, IL-1, GM-CSF and chemokines such as chemokine C-C motif ligand 2 (CCL2) and CCL13." (PMID 25501574, 2014). "Some previous studies have reported that IL6 may participate in the pathogenesis of rheumatoid arthritis (RA), and several clinical trials have been carried out evaluating safety and efficacy of Tocilizumab—an anti-IL6 antibody—in RA patients." (PMID 25544849, 2014). "Since it was reported that Th17 cells are induced by TGF-β, IL-1, IL-6, IL-21 or IL-23, antibodies targeting IL-6 or IL-23 have been considered strong candidates for the development as treatments for autoimmune diseases, including IBD and rheumatoid arthritis." (PMID 24649227, 2013). "The initial observations that IL-6 and later OSM were present in the synovial fluid of rheumatoid arthritis patients stimulated the study of their potential roles in inflammatory joint disease." (PMID 24381786, 2013). "In rheumatoid arthritis, TNF-α, IL-1, IL-6, and IL-17 produced by synovial macrophages and T cells act on osteoblasts to promote RANKL expression." (PMID 23762085, 2013). "This proteinase has been suggested to be induced in response to proinflammatory cytokines such as tumor necrosis factor α (TNFα), interleukin-1 (IL-1), and IL-6 in articular cartilage under pathologic conditions, such as found in OA and rheumatoid arthritis (RA)." (PMID 23951098, 2013). "We compared serum IL-6 level in DM patients with other three connective tissue diseases: systemic lupus erythematosus (SLE), rheumatoid arthritis (RA), and Sjögren's syndrome (SS)." (PMID 24082909, 2013). "We also performed an analysis of gene expression of the cytokines IL-1β and IL-6 and TNFα protein expression, since several studies have shown that inhibition of these cytokines may interfere with the degeneration of articular cartilage and subchondral bone in OA and rheumatoid arthritis." (PMID 24028507, 2013). "We previously reported that IL-29, a newly described member of interferon (IFN) family, was overexpressed in blood and synovium of rheumatoid arthritis (RA) patients and triggered proinflammatory cytokine IL-6 and IL-8 mRNA expression in RA synovial fibroblasts (RA-FLS)." (PMID 24286242, 2013). "Fisetin is known to suppress the production of tumor necrosis factor-α (TNF-α), IL-6, IL-8, and monocyte chemotactic protein-1 (MCP-1) in a rheumatoid arthritis model." (PMID 23710240, 2013). "Feeding patients with rheumatoid arthritis or multiple sclerosis fish oils rich in ω-PUFA, from which RvD1 is derived, can reduce TNF-α and IL-6 levels." (PMID 23199346, 2012). "IL-6 plays a major role in the pathogenesis of rheumatoid arthritis (RA)." (PMID 21951917, 2011). "In rheumatoid arthritis (RA), TNF-α, interleukin (IL)-6, and other proinflammatory cytokines may play a key role in arrhythmogenesis through several mechanisms." (PMID 41517610, 2026). "For instance, in rheumatoid arthritis and psoriatic arthritis, the combination of biologics targeting different inflammatory pathways (e.g., TNF inhibitors with IL-17 or IL-6 blockers) has shown clinical potential in refractory cases, despite limited safety data." (PMID 41488677, 2025).
rheumatoid arthritis (continued). "In rheumatoid arthritis (RA), chronic cytokine-driven inflammation (TNF-α, IL-6) promotes rheumatoid cachexia, accelerating muscle protein breakdown, reducing synthesis, and predisposing to low muscle mass, thereby linking inflammatory activity to creatinine declines via loss of muscle substrate." (PMID 41346979, 2025). "Beyond its link to rheumatoid arthritis by activating synovial fibroblasts, IL-20 also contributes to the development of nephritis by prompting kidney mesangial cells to produce various pro-inflammatory molecules, including MCP-1, RANTES, IP-10, and IL-6." (PMID 39813538, 2025). "Similarly, in rheumatoid arthritis, dysregulated cytokine signaling—particularly involving TNF-α and IL-6—results in persistent joint inflammation and autoimmunity." (PMID 40364844, 2025). "While an association between cholesterol and procalcitonin has not been previously reported, IL-6 inhibition in rheumatoid arthritis is known to increase serum cholesterol levels." (PMID 41007672, 2025). "In contrast, IL-6 inhibits TGF-β-induced Treg differentiation contributing to the dysbalance between Th17/Treg described in several T cell mediated autoimmune diseases such as psoriasis, rheumatoid arthritis (RA), and inflammatory bowel diseases (IBD)." (PMID 40963621, 2025). "B lymphocytes in the peripheral blood of rheumatoid arthritis patients may release many cytokines, including TNF-α, IFN-γ, IL-6, IL-1β, IL-17, and IL-10, which facilitate bone deterioration." (PMID 41127878, 2025). "In rheumatoid arthritis, IL-17 cooperates with TNF and IL-6 to promote synovial fibroblast activation, RANKL upregulation, and erosive damage with synovial tissue atlases identifying Th17-related inflammatory neighborhoods that may modulate treatment response." (PMID 41303386, 2025). "In the realm of inflammatory pain, research has demonstrated the efficacy of extracts derived from genera such as Sargassum, Laminaria, and Ecklonia in significantly downregulating the expression of pro-inflammatory cytokines, including IL-6 and TNF-α, in experimental models of rheumatoid arthritis." (PMID 40710495, 2025). "The histopathological improvements in the AA rat model, paired with the reduction in inflammatory markers, such as TNF-α and IL-6, suggest that BDE is effective in mitigating rheumatoid arthritis pathology through its anti-inflammatory and immunomodulatory effects." (PMID 40332334, 2025). "Additionally, by activating the JNK signaling pathway, PSVII has been shown to suppress the expansion of fibroblasts in rheumatoid arthritis, alleviating symptoms and reducing levels of TNF-α, IL-6, and IL-1β." (PMID 40405066, 2025). "Moreover, the levels of TNF-α and IL-6 are elevated not only in COM but also in other chronic inflammatory conditions like psoriatic arthritis (PsA) and rheumatoid arthritis (RA)." (PMID 40595978, 2025). "In rheumatoid arthritis patients, reduced parasympathetic tone, as measured by HRV, was correlated with higher levels of inflammatory cytokines like tumor necrosis factor-alpha (TNF-α) and interleukin-6 (IL-6)." (PMID 40700127, 2025). "In autoimmune diseases like rheumatoid arthritis (RA) and systemic lupus erythematosus (SLE), inflammatory signals such as TNFα and IL-6 lead to epigenetic reprogramming of SEs, resulting in the aberrant overexpression of pro-inflammatory cytokines such as TNF, IL1 family, and chemokines." (PMID 40895527, 2025). "Tocilizumab, an IL-6 inhibitor used in autoimmune diseases like rheumatoid arthritis and giant cell arteritis, was not administered to our patient cohort, thus precluding its evaluation in those with elevated IL-6 levels." (PMID 38785743, 2024). "While osteoarthritis is not typically classified as an inflammatory arthritis like rheumatoid arthritis, inflammatory cytokines such as IL-1β, IL-6, and TNFα play a role in its pathogenesis." (PMID 39769285, 2024).
rheumatoid arthritis (continued). "Moreover, high levels of inflammatory/arthrogenic factors, including cytokines (TNF-α, IL-6, IL-7, IL-15, and BAFF) and chemokines (CCL-2, CCL-5, and CXCL-10) have been reported in the serum and/or synovia of rheumatoid arthritis patients." (PMID 38720890, 2024). "Approved treatments for rheumatoid arthritis that may work by inhibiting angiogenesis include TNF, IL-1β, and IL-6 inhibitors, thalidomide, and Cox-2 inhibitors." (PMID 38671436, 2024). "and Jaspis. sp., and in an in vivo rat model of complete Freund’s adjuvant rheumatoid arthritis (RA), showed it acted as a SphK1 inhibitor in vitro and significantly improved RA symptoms measured by decreased pro-inflammatory cytokines TNF-α, IL-6, and IL-1β, swelling volume, and arthritis score." (PMID 39057418, 2024). "Previous reports show that IL-1 and IL-6 alone and together downregulate FOXP3 while inducing IL-17 expression on Tregs in a STAT3-dependent way; this is also apparent in EAE and rheumatoid arthritis." (PMID 38386413, 2024). "In addition, multivariate analysis was not included, which limits the ability to assess the possible causes of IL-6 elevation in patients with and without rheumatoid arthritis (RA)." (PMID 39766906, 2024). "For example, stigmasterol treatment reduced TNF-α, IL-6, IL-1β, iNOS and COX-2 in collagen-induced rheumatoid arthritis (RA) rats, and increased the expression of anti-inflammatory cytokines (IL-10) by down-regulating NF-kB p65 and p38 MAPK expression in the joints." (PMID 38579176, 2024). "Piper longum, a medicinal plant from the Piperaceae family, contains major compounds like piperlongumine, an alkaloid, which reduces inflammatory markers such as TNF-α, IL-6, and IL-23, while also inhibiting ROS production and the JNK/NF-kB signaling pathways in rheumatoid arthritis models." (PMID 39866300, 2024). "The correlation analysis of PYCARD with IL-38, IL-6, ESR, anti-CCP, and DAS28 showed that PYCAR was correlated with the disease severity of patients with rheumatoid arthritis as well as other inflammatory factors, and played an important role in rheumatoid arthritis." (PMID 38576041, 2024). "However, regarding IL-6, tocilizumab is a medication that blocks the IL-6 receptor, inhibiting IL-6 signaling; this medication is part of the standard of care for treatment of other autoimmune diseases such as rheumatoid arthritis (RA)." (PMID 41585412, 2024). "Key microRNAs such as miR-143 and miR-145 are upregulated in rheumatoid arthritis fibroblast-like synoviocytes, targeting IGFBP5 and SEMA3A, resulting in elevated IL-6 production, NF-κB activation, and improved fibroblast-like synoviocyte survival and motility." (PMID 39530095, 2024). "Activation of A2AR inhibits NF-κB signaling pathway and inflammatory cytokine (IL-1, IL-6, TNF, IFN) production, and increases the anti-inflammatory cytokine IL-10 release, which leads to autoimmune diseases such as rheumatoid arthritis, systemic lupus erythematosus, or type 1 diabetes." (PMID 38837964, 2024). "For example, CRP is less likely to be elevated under anti-IL-6 receptor antibody therapy in patients with rheumatoid arthritis since the release of CRP is affected by IL-6; therefore, it is not useful for assessing disease activity." (PMID 38002777, 2023). "Similarly, atorvastatin revealed a potential immunomodulatory effect against rheumatoid arthritis by reducing IL-17A, TNF, and IL-6 levels." (PMID 38105357, 2023). "Theophylline is an anti-inflammatory substance, and previous studies have shown that theophylline can reduce the levels of IL-6, COMP, JAK2, STAT3, RANKL, iNOS, and eNOS by modulating the JAK/STAT/RANKL signaling pathway, thereby alleviating the inflammatory response in rheumatoid arthritis." (PMID 37076836, 2023). "In contrast, IL-6 antibodies failed in phase II clinical trials for IBD due to non-tolerable side effects, including intestinal perforations which were also observed for anti-IL-6R therapy for rheumatoid arthritis." (PMID 37838173, 2023).
rheumatoid arthritis (continued). "Additionally, hesperidin was shown to reduce the production of IL-1β, IL-6, and TNF-β in a rat model of rheumatoid arthritis." (PMID 37020549, 2023). "In rheumatoid arthritis (RA), IL-17-producing Th17 cells reportedly induce local inflammation by stimulating production of IL-6, IL-1, TNFα and chemokines, and IL-17 may directly stimulate synovial fibroblasts to induce RANKL expression, which in turn, results in bone destruction." (PMID 38062130, 2023). "Importantly, therapies targeting IL-6 and IL6R are approved for several conditions including rheumatoid arthritis, cytokine release syndrome, giant cell arteritis, and multicentric Castleman disease." (PMID 36599350, 2023). "Increased levels of IL-4, IL-6, TNF-α, IL-10, and IL-17 have been reported in rheumatoid arthritis." (PMID 37111383, 2023). "It is believed that anti-IL6 therapy reduces inflammation and has anti-angiogenic effects, with therapeutic effects in Castleman’s disease and inflammatory diseases (rheumatoid arthritis) without significant toxicity." (PMID 37304306, 2023). "Importantly, in untreated rheumatoid arthritis (RA) patients, expression of Arid5a in CD4+ T cells is increased, whereas treatment with the anti-IL-6 receptor antibody tocilizumab is associated with decreased Arid5a expression, indicating that the IL-6-ARID5a axis may be involved in RA pathogenesis." (PMID 36408139, 2022). "It has been shown that IL-6 could activate STAT3 through Janus-activated kinases (Jak), and rheumatoid arthritis patients treated with anti-Jak inhibitors in vitro saw an inhibition of lymphocyte autophagy." (PMID 36590587, 2022). "Both IL-6 and TNF-α play critical roles in the immunopathogenesis of rheumatoid arthritis." (PMID 35009001, 2022). "In rheumatoid arthritis synovial fibroblasts, calycosin significantly potentiated Nrf2 translocation by inducing p62 accumulation and Keap1 degradation to activate HO-1 and NQO1, thus suppressing IL-6 and IL-33 secretion and COX-2 mRNA and protein expression." (PMID 36358507, 2022). "S100A4 is a potent trigger of inflammatory molecules, such as interleukin (IL)-1, IL-6, tumor necrosis factor (TNF)-a, and matrix metalloproteinases, which are involved in autoimmune disease developments, such as allergies, rheumatoid arthritis, systemic sclerosis, and psoriasis, etc.." (PMID 36361563, 2022). "Tocilizumab, an antibody against IL-6, used to reduce the cytokine storm, seems to increase anabolic muscle processes in the long-term, as demonstrated by DXA(Osteodensitometry) measurements in rheumatoid arthritis patients." (PMID 36143878, 2022). "In rheumatoid arthritis synovial fibroblasts, the expression of TRPV1 and TRPA1 and the regulation of related receptors by endogenous agonists have been shown to reduce the production of IL-6, IL-8 and MMP-3." (PMID 36278189, 2022). "CXCL1 also increases the production of IL-6 in FLS, one of the factors causing an increase in IL-6 in synovial fluid in patients with rheumatoid arthritis; such a response does not occur in healthy individuals." (PMID 35457023, 2022). "In patients with rheumatoid arthritis, a negative correlation of the levels of IL-1RA, IL-6, and CXCL8 with the expression of the CYP3A4 phenotype of the CYP family was detected." (PMID 35408801, 2022). "In response to IL-6 stimulation, the JAK/STAT3 pathway is phosphorylated, forming the critical IL-6/JAK/STAT3 pathway in the human body, which is involved in the processes of rheumatoid arthritis, inflammatory bowel disease, and many human cancers." (PMID 36291659, 2022). "What is more, previous studies have reported that the expression levels of IL6 and IL10 are downregulated in patients with rheumatoid arthritis however, in our research we have found that mitotransfer significantly enhanced their amount on mRNA and protein levels." (PMID 36071528, 2022).
rheumatoid arthritis (continued). "Swollen 28-joint count (SJC-28), Tender 28-joint count (TJC-28), CRP, erythrocyte sedimentation rate (ESR), uncarboxylated osteocalcin (UCOC), MMP-3, TNF, IL-6, and DAS28-ESR (Diseases Activities Score-28 for Rheumatoid Arthritis with ESR) levels are also decreased." (PMID 34770980, 2021). "Downregulation of PTGS2 reduces the expression of IL-6 and MMP-3, and the downregulation of MMP-3 and PTGS2 have been shown to help inhibit synovial fibroblast proliferation and joint inflammation in rheumatoid arthritis." (PMID 34917160, 2021). "A recent study described Treg perturbations in rheumatoid arthritis joints that are reminiscent of those described here (in particular with elevated FoxP3 MFI), an interesting parallel since the arthritic joint is high in IL-6." (PMID 34433692, 2021). "MiR-26b has been associated to RA and inflammation where inhibition of miR-26b in rheumatoid arthritis fibroblast-like synoviocytes (RAFLS) causes increased levels of TNF-α, IL-1β, and IL-6, while miR-26b mimics mediate downregulation of the same proinflammatory cytokines." (PMID 33210166, 2021). "This hypothesis is supported by accumulation of ICR expressing T cells during chronic inflammatory diseases such as Crohn’s, ulcerative colitis and rheumatoid arthritis, mainly maintained by TNF-α, IFN-γ, and IL-6, that are also seen in CL lesions." (PMID 33767700, 2021). "We show that the expression of IL-1β or IL-6 inducible transcriptional signatures (modules) reflects the bioactivity of these cytokines in immunopathology modelled by juvenile idiopathic arthritis (JIA) and rheumatoid arthritis." (PMID 33319166, 2021). "It has been demonstrated that osteocytes are implicated in inflammatory diseases such as rheumatoid arthritis and may produce interleukin (IL)-1β, IL-6, and tumor necrosis factor-α (TNF-α) to mediate bone destruction in rheumatoid arthritis pathogenesis." (PMID 34093433, 2021). "Finally, the anti-rheumatoid arthritis effects of the four target compounds were validated with the decreased levels of NO, TNF-α, IL-6 and IL-1β in RAW 264.7 macrophage cells treated with LPS." (PMID 34526896, 2021). "Research demonstrates that angiogenesis can be hampered under an environment of inflammation as well as impede the inflammation-induced expression of VEGF in MH7A cell partly through the pathway IL-6/JAK2/STAT3/VEGF, providing new prospects for treating rheumatoid arthritis." (PMID 33499333, 2021). "It is an important immunosuppressive protein because it regulates expression of several inflammatory cytokines/chemokines, including interleukin 6 (IL-6), interleukin 8 (IL-8), and CCL2, which have been reported in the pathogenesis of rheumatoid arthritis, psoriasis, and multiple sclerosis." (PMID 34877932, 2021). "In rheumatoid arthritis, KPNA2 was shown to be a trigger of interleukin 6 (IL-6) secretion, colocalized with T cells and neutrophils, and could be upregulated via tumor necrosis factor α stimulation." (PMID 33193737, 2020). "Additionally, a significant decrease in the levels of IL-6, TNF-α and IFN-γ was found in patients with rheumatoid arthritis and psoriasis treated with itolizumab." (PMID 33292350, 2020). "The pathophysiology of rheumatoid arthritis (RA) is characterized by excess production of pro-inflammatory cytokines, including tumor necrosis factor-α (TNF-α), interleukin-1β (IL-1β), and interleukin-6 (IL-6) by neutrophils and macrophages in synovium." (PMID 32131874, 2020). "The proinflammatory cytokines such as IL-1β, IL-6, TNF, CXCL9, CXCL10, and IFN-γ participate in the pathology of several chronic inflammatory diseases including rheumatoid arthritis, coronary diseases, cerebral malaria, tegumentary leishmaniasis, and Chagas diseases." (PMID 32385802, 2020).